OR6N2 (olfactory receptor family 6 subfamily N member 2)
Description:
Odorant receptor.
Synonyms: OR1-23
Tractability: Antibody: UniProt places it where antibodies can reach, with medium confidence; UniProt predicts a signal peptide or a membrane-spanning region; its Gene Ontology location is reachable by antibodies, with medium confidence.
Gene: Protein-coding gene on chromosome 1 (158,774,222 to 158,781,204, reverse strand). Ensembl gene ENSG00000188340.
Subcellular location: Cell membrane
Pathways (Reactome):
Sensory Perception: Expression and translocation of olfactory receptors
Gene Ontology:
Molecular function: odorant binding; olfactory receptor activity; G protein-coupled receptor activity
Biological process: detection of chemical stimulus involved in sensory perception of smell; G protein-coupled receptor signaling pathway
Cellular component: membrane; plasma membrane
Genetic constraint (gnomAD): Loss-of-function variants: 0 observed, 0.12 expected, observed/expected ratio (o/e) 0, 90% interval 0 to 1.89. That is too few expected variants to judge how well the gene tolerates losing a copy. Missense variants: 389 observed, 391.23 expected, observed/expected ratio (o/e) 0.99, 90% interval 0.91 to 1.08. Synonymous variants: 155 observed, 143.86 expected, observed/expected ratio (o/e) 1.08, 90% interval 0.94 to 1.23.
Homologues: Orthologues: chimpanzee OR6N2 (98% identical), macaque OR6N2 (95% identical), dog OR6N2 (88% identical), pig OR6N2 (88% identical), rabbit OR6N2 (88% identical), mouse Or6n2 (86% identical), rat Or6n2 (85% identical), guinea pig OR6N2 (83% identical). Paralogues in human: OR6N1 (65% identical), OR6K3 (51% identical), OR6K2 (50% identical), OR6K6 (50% identical), OR10Z1 (43% identical), OR1L1 (42% identical), OR10K1 (41% identical), OR10R2 (41% identical), OR1E1 (41% identical), OR1F1 (41% identical), OR1L3 (41% identical), OR1L6 (41% identical), and 116 more.
Diseases named in the same sentence as OR6N2 in open-access papers:
OR6N2 is named in the same sentence as 3 diseases in open-access papers, as found by Europe PMC text mining. Sharing a sentence is not in itself a finding about the gene and the disease. The quoted sentences say what the papers report.
cancer (1 paper, 2022). A tumor composed of atypical neoplastic, often pleomorphic cells that invade other tissues. "Genes such FAM182A, SOX9, AHNAK2, ENSG00000121031, FLT3LG, PMEPA1, ZFP36L2 in the large intestine, ALB, KRTAP19-1, APOB, CD200, CRYGD, KRTAP24-1, OR6N2 in the liver are novel predictions, and their functions in these cancers can further be studied." (PMID 34997044, 2022).
OR6N2 also shares sentences with these, for which no sentence is quoted: autism (1 paper); entropion (1).